IGHG2 (immunoglobulin heavy constant gamma 2 (G2m marker))
Description:
Constant region of immunoglobulin (Ig) heavy chains. Igs are membrane-bound or secreted glycoproteins produced by B lymphocytes. In the recognition phase of humoral immunity, the membrane-bound Igs serve as receptors, which upon binding to a specific antigen trigger the clonal expansion and differentiation of B lymphocytes into Ig-secreting plasma cells. Secreted Igs known as antibodies mediate the effector phase of humoral immunity by blocking the interaction of infectious antigens with cellular receptors (via the antigen-binding region) and eliciting effector mechanisms that lead to pathogen neutralization (via the constant region). The antigen-binding region is formed by the variable domain of one heavy chain paired with the variable domain of its associated light chain. Each Ig molecule has two antigen-binding sites with remarkable affinity for a particular antigen due to V-(D)-J rearrangement, somatic hypermutations and affinity maturation of the variable domains upon antigen exposure. The constant region defines the Ig isotype that perform distinct sets of effector functions. B cells diversify and rearrange their Ig constant regions through class-switch recombination, a process by which the constant region is switched from one Ig isotype to another, namely from IgM and IgD to IgG, IgA and IgE. The constant region interacts (via the fragment crystallizable, Fc) with receptors on innate immune cells and the complement system to mediate humoral effector functions. Ig gamma-2 (IgG2) isotype formed against polysaccharide structures found on encapsulated bacteria elicits antibody-dependent protection through activation of complement pathway.
Tractability: Antibody: its Gene Ontology location is reachable by antibodies, with high confidence; UniProt places it where antibodies can reach, with medium confidence; UniProt predicts a signal peptide or a membrane-spanning region. PROTAC: its protein half-life has been measured.
Gene: Immunoglobulin constant (C) gene on chromosome 14 (105,639,559 to 105,644,790, reverse strand). Ensembl gene ENSG00000211893.
Subcellular location: Secreted (Isoform 1); Cell membrane (Isoform 2)
Pathways (Reactome):
Immune System: Classical antibody-mediated complement activation; FCGR activation; Initial triggering of complement; Regulation of Complement cascade; Regulation of actin dynamics for phagocytic cup formation; Role of phospholipids in phagocytosis
Disease: FCGR3A-mediated IL10 synthesis; FCGR3A-mediated phagocytosis
Gene Ontology:
Molecular function: protein binding; antigen binding; immunoglobulin receptor binding
Biological process: adaptive immune response; antibacterial humoral response; B cell receptor signaling pathway; complement activation, classical pathway
Cellular component: blood microparticle; extracellular exosome; extracellular region; IgG immunoglobulin complex; immunoglobulin complex, circulating; plasma membrane
Homologues: Paralogues in human: IGHG4 (93% identical), IGHG3 (93% identical), IGHG1 (93% identical), IGHE (36% identical), IGHM (32% identical), IGHA1 (29% identical), IGHA2 (28% identical), IGHD (24% identical), IGLL1 (12% identical), IGLL5 (12% identical), IGLC1 (9% identical), IGLC7 (9% identical), and 65 more.
Diseases named in the same sentence as IGHG2 in open-access papers:
IGHG2 is named in the same sentence as 29 diseases in open-access papers, as found by Europe PMC text mining. Sharing a sentence is not in itself a finding about the gene and the disease. The quoted sentences say what the papers report.
COVID-19 (3 papers, 2023 to 2024). A disease caused by infection with severe acute respiratory syndrome coronavirus 2. "There are five classes of immunoglobulins: IgA, IgD, IgE, IgG, and IgM, and the expression of IGHG1 and IGHG2, the subtype of IgG, tended to be higher in the HD-COVID-19 group, whereas IGHM was higher in the HDs with vaccine group." (PMID 36911681, 2023). "Specifically, signatures of plasma cells (IGHG3, IGKC, IGHM, JCHAIN, IGHG2, IGKV4-1, IGLV3-1, IGHA1), activated fibroblasts (COL1A1, COL1A2, COL3A1), inflammatory cytokines (CXCL9, CCL18) and complement factors (C1QB, C1QC) dominated the DE genes for the COVID-19 lung sections." (PMID 37858234, 2023).
cervical carcinoma (2 papers, 2014 to 2025). A carcinoma arising from either the exocervical squamous epithelium or the endocervical glandular epithelium. "In other cancer types, IGHG2 has been reported, particularly in carcinomas, such as head and neck squamous cell carcinoma, oral squamous cell carcinoma, and cervical carcinomas, as well as others like glioblastoma, although they are mainly related to prognosis." (PMID 40565234, 2025). "It should be pointed that we selected IGHG1 for the silencing target only rather than IGHG2, IGHG3 and so on because knockdown of endogenous IGHG1 could lead to more significant biological effects than that of others in cervical cancer cells according to our preliminary experiments." (PMID 25179302, 2014).
head and neck squamous cell carcinoma (2 papers, 2022 to 2025). A squamous cell carcinoma that arises from any of the following anatomic sites: lip and oral cavity, nasal cavity, paranasal sinuses, pharynx, larynx, and salivary glands. "High expression of IGHG2 is also a positive survival parameter in different solid tumors when validated using TCGA (The Cancer Genome Atlas) data, including head and neck squamous cell carcinomas (TCGA-HNSCC) and breast invasive carcinoma (TCGA-BRCA)." (PMID 35812448, 2022).
Autoimmunity (1 paper, 2022). The occurrence of an immune reaction against the organism's own cells or tissues. "We found that autoreactive IGHV4-34 BCRs, which are elevated in autoimmunity, were significantly depleted in IGHD/M but elevated in class-switched B cells, most notably for the IGHA2 and IGHG2 B cells consistent with class-switching of these autoreactive B cells during the response to SARS-CoV-2." (PMID 35216673, 2022).
breast carcinoma (1 paper, 2024). "IGHG2 exhibited high expression in estrogen receptor-positive) and HER2 + (and human epidermal growth factor receptor 2-positive) breast cancer." (PMID 38388382, 2024). "IGHG2 expression is significantly higher in ER + and HER2 + breast cancer." (PMID 38388382, 2024).
Cachexia (1 paper, 2022). Severe weight loss, wasting of muscle, loss of appetite, and general debility related to a chronic disease. "B cells from patients with cachexia showed lower expression of MHC-II molecules (HLA-DRB5, HLA-DQA2) and higher expression of the immunoglobulins (IGHG2, IGHG3, IGKC), and genes involved in BCR signaling." (PMID 36376273, 2022).
influenza (1 paper, 2024). An acute viral infection of the respiratory tract, occurring in isolated cases, in epidemics, or in pandemics; it is caused by serologically different strains of viruses (influenzaviruses) designated A, B, and C, has a 3-day incubation period, and usually lasts for 3 to 10 days. "Reanalysis of prior PBMC RNA-seq data on influenza vaccine responses in younger adults showed upregulated expression of IGHG1 and IGHG3 at day 7, whereas pneumococcal vaccines upregulated the expression of IGHA2 and IGHG2." (PMID 38182669, 2024).
oral cancer (1 paper, 2022). "The top 3 IRGPs most strongly and positively correlated with the outcome of oral cancer were TNFRSF12A|TNC, PLAU|DEFB1, and TAP|IGHG2." (PMID 35804390, 2022).
rectal cancer (1 paper, 2021). A primary or metastatic malignant neoplasm that affects the rectum. "After neoadjuvant chemoradiotherapy, the expression level of IGHG2 increased significantly in rectal cancer, indicating that IGHG2 was originally with a low expression in tumor cells and existed as a protective factor, which was consistent with our prognostic analysis." (PMID 35237609, 2021).
Sepsis (1 paper, 2025). Sepsis is defined as life-threatening organ dysfunction caused by a dysregulated host response to infection. "Furthermore, several immunoglobulin genes including membrane and secreted forms of IGHM, IGHG1 and IGHG2 were also reduced in sepsis patients." (PMID 41208955, 2025).
Stroke (1 paper, 2024). Sudden impairment of blood flow to a part of the brain due to occlusion or rupture of an artery to the brain. "We found that tissue containing microglia nodules in MS had significant upregulated Ig genes (IGKC, IGHG1, IGHG2, and IGKV3-15) compared to tissue containing stroke nodules." (PMID 38396116, 2024). "Also, we found significantly upregulated expression of the Ig genes IGKC, IGHG1, IGHG2, and IGKV3-15 in MS nodule NAWM tissue as compared to stroke." (PMID 38396116, 2024).
viral infections (1 paper, 2023). "Interestingly, the elevated IgG gene expression was mainly due to IgG1 (IGHG1) and IgG3 (IGHG3), but not IgG2 (IGHG2), which is in line with the presumed IgG1- and IgG3-switched phenotype of T-bet+ B cells both in MS and during viral infections." (PMID 36796230, 2023).
tumor (9 papers, 2017 to 2025). "This suggests that the protein expression of OSMR, IGFBP6, and IGHG2 was significantly elevated in the tumor tissue of GBM patients compared to normal control tissue." (PMID 39815665, 2025). "In the HPA database, only OSMR, IGFBP6, and IGHG2 were found, showing high levels of protein expression in tumor tissue of GBM patients for all three." (PMID 39815665, 2025). "The results showed that compared with HSKMC, PODXL2, LRRC17, GABRA3, SCUBE3, and RFLNB were highly expressed in tumor cells, while IGHG2 and HLF were low expressed." (PMID 36155774, 2022). "However, eight of the known antigens (the exception being IGHG2) had been shown to play a role in various tumour types previously." (PMID 36008952, 2022). "The results indicated that in GBM tumor tissue, OSMR and FMOD were primarily distributed in astrocytes, IGFBP6 in NPC, G0S2 in macrophages, and IGHG2 in T cells." (PMID 39815665, 2025). "In summary, the mRNA expression of OSMR, G0S2, IGHG2, and FMOD was significantly upregulated in tumor tissue of GBM patients compared to normal control tissue." (PMID 39815665, 2025). "To investigate the role of the five genes (OSMR, G0S2, IGFBP6, IGHG2, and FMOD) in specific cells within the tumor tissue of GBM patients, we illustrated the distribution of these genes across different cell types." (PMID 39815665, 2025). "It is worth noting that IGHG2 also demonstrated prognostic significance in this study and was recognized as differentially expressed in the NPC tumor proteome study." (PMID 40565234, 2025). "So far, no studies have shown that these seven genes (IGHG2, PODXL2, LRRC17, GABRA3, SCUBE3, HLF and RFLNB) are directly related to pyroptosis in tumor cells." (PMID 36155774, 2022).
cancer (8 papers, 2018 to 2025). A tumor composed of atypical neoplastic, often pleomorphic cells that invade other tissues. "Among them, C8A and C4B may play a relevant role in CRC progression, while the immunoglobulin IGHG2 may be associated with the immune response in CRC early stages by promoting inflammation as enhanced levels were linked to cancer-associated inflammation." (PMID 38911905, 2024). "A comparison early-stage and late-stage CRC patients revealed 4 potential biomarkers associated with cancer progression, including C4B, C8A, APOC2, and IGHG2." (PMID 38911905, 2024). "IGHG2 has a positive prognostic effect in many other cancer types when examined using TCGA data." (PMID 35812448, 2022). "Moreover, IGHG2, HPT, and A2MG identified in stool-related cancer samples, along with catalase detected in advanced pre-cancerous lesions, have been previously reported elevated in both cancerous and advanced non-cancerous lesions." (PMID 38612533, 2024).
infection (2 papers, 2022 to 2023). The state of being infected such as from the introduction of a foreign agent such as serum, vaccine, antigenic substance or organism. "An increased expression of IGHG1, IGHG2, IGHG3, IGLV3-21, and IGLV6-57 was noted during active infection at 0 weeks compared with that at 8 weeks." (PMID 37434783, 2023). "We reported a high expression of IGHG family (IGHG1, IGHG2, and IGHG3) and IGLV family (IGLV3-21 and IGLV6-57) at 0 weeks, which are clinically correlate with active infection." (PMID 37434783, 2023). "For example, IGHA2 and IGHG2 were significantly increased after vaccination while they were not significant changed after infection." (PMID 35686122, 2022).
bacterial infections (1 paper, 2022). "In contrast, IGHG2, typically related to response to bacterial infections, was not induced." (PMID 36496417, 2022).
IGHG2 also shares sentences with these, for which no sentence is quoted: glioblastoma (2 papers); bladder cancer (1); breast invasive carcinoma (1); Crohn disease (1); dysplasia (1); endothelial dysfunction (1); epilepsy (1); Insulin resistance (1); liver cancer (1); melanoma (1); oral squamous cell carcinoma (1); polycystic kidney disease (1); sarcoma (1).